TCF7L1 (transcription factor 7 like 1)
Diseases named in the same sentence as TCF7L1 in open-access papers (continued):
Sharing a sentence is not in itself a finding about the gene and the disease.
chloroma (1 paper, 2021). "The backward elimination procedure identified RUNX1T1, MAPK3, PIK3CG, TCF7L1, GRB2, and MTOR as the empirical drivers of the association with chloroma." (PMID 33882829, 2021).
colorectal tumour (1 paper, 2022). "In addition, overexpression of TCF7L1 can induce the growth of colorectal tumour cells." (PMID 36105798, 2022).
condyloma acuminatum (1 paper, 2016). "We found that both Tcf7l1 and LCN2 were highly expressed in those diseases characterized by defective keratinocyte differentiation (especially psoriasis vulgaris, condyloma acuminatum, squamous cell carcinoma, etc)." (PMID 27551519, 2016).
endometriosis (1 paper, 2025). The growth of functional endometrial tissue in anatomic sites outside the uterine body. "Moreover, a significant downregulation of several potential targets, including CDK6, BCCIP, PTEN, TCF7L1, TCF7L2, ROBO1, COL4A2, E‐Cadherin, and N‐Cadherin, was observed in the transfected cells and endometriosis patients." (PMID 40135061, 2025).
germ cell tumor (1 paper, 2023). A benign or malignant, gonadal or extragonadal neoplasm that originates from germ cells. "TCF7L1, a WNT suppressor, can sensitively distinguish TGCT from nonseminomatous germ cell tumors." (PMID 37543714, 2023).
hypopituitarism (1 paper, 2020). A condition of diminution or cessation of secretion of one or more hormones from the anterior pituitary gland. "Mutations in TCF7L1 and TGIF1 have been reported in patients with hypopituitarism recently." (PMID 33077725, 2020).
mesothelioma (1 paper, 2022). A usually malignant and aggressive neoplasm of the mesothelium which is often associated with exposure to asbestos. "Importantly, immunohistochemical staining of SDC2 and TCF7L1 in metastatic MESO tissue was more intense than that in nonmetastatic mesothelioma tissue, and this difference reached statistical significance (P < 0.05, Welch's t-test)." (PMID 35127947, 2022).
nevus (1 paper, 2016). Nevus (or naevus, plural nevi or naevi, from nævus, Latin for "birthmark") is the medical term for sharply circumscribed[1] and chronic lesions of the skin or mucosa. "The overexpression of Tcf7l1 and LCN2 in melanocytes of pigmented nevus suggests an additional function of the Tcf7l1–LCN2 axis, which should be elucidated in other studies." (PMID 27551519, 2016).
papilloma (1 paper, 2017). A benign epithelial neoplasm that projects above the surrounding epithelial surface and consists of villous or arborescent outgrowths of fibrovascular stroma. "Under a high-dose DMBA (100 nmol) and TPA (10 nmol) treatment, TCF7L1-induced mice developed a greater number of papillomas at a faster rate than control mice did (n = 17 TCF7L1-induced, n = 16 control)." (PMID 28467300, 2017). "In summary, we established that TCF7L1 promotes the development of papilloma and skin SCC, affecting both the early step of tumor formation as well as the progression step into malignancy in the DMBA/TPA model." (PMID 28467300, 2017). "Using the tet-inducible Tcf7l1 transgenic mouse model to mimic the upregulation of TCF7L1 found in papilloma and skin SCC, we demonstrated that TCF7L1 overexpression promotes and accelerates both premalignant papilloma formation and progression into SCC." (PMID 28467300, 2017). "To assess the role of TCF7L1 in skin SCC, we first evaluated the expression pattern of TCF7L1 in DMBA/TPA-induced mouse papillomas and skin SCC." (PMID 28467300, 2017). "Coincidentally, Tcf7l1 mRNA is highly expressed in mouse papillomas, which are premalignant lesions that precede SCC." (PMID 28467300, 2017). "In contrast to control animals that experienced a lower than 20% frequency of tumor formation, 80% of TCF7L1-induced animals formed papilloma and 60% developed SCC (n = 16 TCF7L1-induced, n = 21 control)." (PMID 28467300, 2017). "While 100% of animals developed papillomas under the high-dose regimen, the effect of TCF7L1 overexpression was much more evident upon a low dose of DMBA (25 nmol) and TPA (1 nmol)." (PMID 28467300, 2017). "Although TCF7L1 expression is normally restricted to the bulge and outer root sheath cells of the hair follicle and is absent in the interfollicular epidermis, we observed widespread expression in papillomas and even greater expression in skin SCC." (PMID 28467300, 2017). "This hypothesis was supported by the finding that β-catenin is essential for the development and growth of papillomas in a murine skin SCC model, and that Tcf7l1 mRNA is upregulated in papilloma." (PMID 28467300, 2017). "Since β-catenin is critical for tumor growth in the DMBA/TPA model of skin SCC, and both nuclear β-catenin and Tcf7l1 mRNA are upregulated in papillomas, it was thought that TCF7L1’s tumor-promoting role might depend on its binding to β-catenin in the canonical WNT signaling pathway." (PMID 28467300, 2017). "Since overexpression of TCF7L1 increased papilloma incidence but not papilloma size, we postulate that TCF7L1 facilitates the transformation of mutated cells into premalignant state and contributes little to growth of papilloma." (PMID 28467300, 2017). "Moreover, since TCF7L1-induced mice developed more SCCs, we speculate that overexpression of TCF7L1 also stimulates the progression of papilloma into malignancy." (PMID 28467300, 2017). "Our finding that TCF7L1 overexpressing mice developed papilloma at a higher number and at an earlier time under both DMBA/TPA or DMBA alone treatment indicates that TCF7L1 overexpression contributes to the early step of tumor formation." (PMID 28467300, 2017). "In the UV-induced mouse model of skin SCC, where papillomas and SCC develop from skin that is chronically exposed to UV radiation, increased expression of TCF7L1 was also observed in 2 out of 4 cases of skin SCC examined." (PMID 28467300, 2017). "We found that while almost none of the control mice developed tumors, over 30% of the TCF7L1-induced mice developed papilloma (n = 22 TCF7L1-induced, n = 26 control)." (PMID 28467300, 2017). "Although TCF7L1-overexpressing skins are hyperproliferative, control and TCF7L1-induced papilloma do not differ in size." (PMID 28467300, 2017).
papilloma (continued). "However, it should be noted that while overexpression of TCF7L1 increased the incidence of papilloma development in DMBA/TPA treated mice, it did not increase the average size of papilloma (data not shown)." (PMID 28467300, 2017). "Since overexpression of TCF7L1 did not stimulate proliferation of DMBA/TPA induced papilloma per se and did not promote tumor development without DMBA treatment, it suggests that TCF7L1 may facilitate the transitioning of DMBA-induced mutated cells into premalignant tumors." (PMID 28467300, 2017).
prostate adenocarcinoma (1 paper, 2021). "In order to evaluate the contribution of WNT4/TCF7L1 to the malignant progression of human prostate adenocarcinomas, AR-positive C4-2 and LNCaP cells stably expressing TCF7L1 were treated with the WNT4 protein." (PMID 34799554, 2021).
prostate tumors (1 paper, 2021). "Herein, we aimed to understand if TCF7L1 is highly upregulated in prostate tumors after ADT, compared to hormone-naïve prostate patients." (PMID 34799554, 2021). "A novel regulatory role for the candidate prostate tumor promoter, TCF7L1, was identified." (PMID 34799554, 2021).
sarcoma (1 paper, 2024). A usually aggressive malignant neoplasm of the soft tissue or bone. "Additionally, miR-329-3p was inversely linked with TCF7L1 expression in sarcoma tissue and had a certain prognostic effect, according to the findings of an investigation of the TCGA database, which contained clinical data from 261 cases." (PMID 38370338, 2024).
skin papilloma (1 paper, 2017). A benign papillary neoplastic growth on the skin composed of epithelial cells and a fibrous stalk. "We showed that overexpression of TCF7L1 induced expression of LCN2 in vivo as previously reported and that expression of LCN2 was also induced in murine skin papilloma and SCC similarly to TCF7L1." (PMID 28467300, 2017).
skin tumor (1 paper, 2017). "Since TCF7L1 overexpression promoted and accelerated skin tumor development, we explored possible mechanisms underlying this role." (PMID 28467300, 2017).
tumor (26 papers, 2011 to 2026). "Our findings establish a tumor-promoting role for TCF7L1 in skin and elucidate the mechanisms underlying its tumorigenic capacity." (PMID 28467300, 2017). "Various classes of tumor tissues exhibit upregulated expression of TCF7L1, which modulates tumor biological behavior and may be associated with poor prognosis." (PMID 38370338, 2024). "Our study discovered a causative link between TCF7L1 up-regulation and cancer-associated inflammation in skin tumorigenesis, suggesting that TCF7L1 may facilitate tumor growth through induction of a subset of cytokines in a paracrine manner." (PMID 28467300, 2017). "To test whether LCN2 is a major downstream effector of TCF7L1 that stimulates tumor growth, we took a combined gain- and loss-of-function strategy." (PMID 28467300, 2017). "Remarkably, LEF1 shares with TCF7L1 this stronger link to cell adhesion in tumor tissue, and also an association in normal tissue with muscle, which seems difficult to explain, but could somehow be linked to shared molecular machinery functioning in cell migration." (PMID 32403323, 2020). "Conversely, knocking down HSPB6 expression partly reversed these effects, suggesting the tumor-suppressive impact of TCF7L1 overexpression is modulated by HSPB6 expression levels." (PMID 39608715, 2024). "Rescue experiments further confirmed TCF7L1's role in inhibiting tumor growth in BLCA, demonstrating that overexpressing TCF7L1 leads to a reduction in cell proliferation, migration, and invasion, alongside an increase in apoptosis within tumor cells." (PMID 39608715, 2024). "In colorectal cancer, TCF7L1 positively regulates cell proliferation, and suppressing its expression in xenografts results in tumor size reduction." (PMID 38370338, 2024). "Although these studies primarily focused on the effects of TCF7L1 on tumor cell proliferation and identified several miRNAs targeting TCF7L1, there is a pressing need for more in-depth investigation into the regulation of TCF7L1 by miRNA in OS." (PMID 38370338, 2024). "EdU assays illustrated that TCF7L1 overexpression diminished tumor cell proliferation, a phenomenon mitigated upon concurrent HSPB6 depletion." (PMID 39608715, 2024). "Xenograft experiments indicated that the overexpression of miR-329-3p significantly inhibited the growth of OS xenografts in nude mice, and the expression of TCF7L1 and c-Myc in tumor tissues decreased." (PMID 38370338, 2024). "Immunohistochemical analyses conducted on tumor tissues further revealed a notable reduction in TCF7L1 and c-Myc expression within OS cells in vivo." (PMID 38370338, 2024). "Overexpression of miR-329-3p suppressed TCF7L1 expression, underscoring its role as a tumor suppressor in OS cells." (PMID 38370338, 2024). "In summary, this study reveals that the expressions of HSPB6 and TCF7L1 are both downregulated in the tumor tissues of BLCA patients." (PMID 39608715, 2024). "A tumour-specific upregulation of Lef1 and Tcf7 genes was observed, as well as downregulation of Tcf7l1, while Tcf7l2 expression was unaltered." (PMID 37907668, 2023). "Based on the literature, the role of TCF7L1 is equivocal but some research indicate that it acts as a tumor suppressor and inhibits metastasis." (PMID 35563688, 2022). "In different kinds of human cancer, it has been found that the TCF7L1 gene is abnormally expressed in tumor tissues and has tumor regulatory function." (PMID 33824876, 2021). "Cell adhesion-associated gene expression is correlated with TCF7L2 expression specifically in normal tissue, and with LEF1 and TCF7L1 in tumor tissue." (PMID 32403323, 2020). "Extracellular matrix-associated gene expression is also correlated with TCF7L1 specifically in normal tissue and with LEF1 expression exclusively in tumor tissue." (PMID 32403323, 2020). "Through transcriptome profiling and combined gain- and loss-of-function studies, we identified LCN2 as a major downstream effector of TCF7L1 that drives tumor growth." (PMID 28467300, 2017).
tumor (continued). "We found that full-length TCF7L1 overexpression significantly increased tumor size relative to the control while TCF7L1*, which cannot bind to DNA, had little effect." (PMID 28467300, 2017). "Using separation-of-function mutants, we show that TCF7L1 promotes tumor growth, enhances cell migration, and overrides oncogenic RAS-induced senescence independently of its interaction with β-catenin." (PMID 28467300, 2017). "Using a xenograft model of human skin SCC, we demonstrated that TCF7L1 stimulates tumor growth, suppresses oncogene-induced senescence, and accelerates tumor cell migration, independently of its interaction with β-catenin." (PMID 28467300, 2017). "It is thus possible that TCF7L1 overexpression increases tumor incidence and/or progression by promoting the proliferation of quiescent stem cells with oncogenic mutations." (PMID 28467300, 2017). "In a xenograft model of human skin SCC, we show that overexpression of TCF7L1 also promotes tumor growth while downregulation of TCF7L1 and its paralogue TCF7L2 decreases tumor growth." (PMID 28467300, 2017). "In this study, we show that overexpression of TCF7L1 increases tumor incidence, multiplicity, and malignant conversion in a mouse model of skin SCC." (PMID 28467300, 2017). "For example, does dysregulation of TCF7L1/FOXA2 lead to loss of differentiated features, a hallmark of anaplastic tumours?" (PMID 26675138, 2016). "TCF7L1 encodes a TF in the WNT pathway which regulates the expression of cell cycle related genes and is a central regulator of tumor growth and initiation; DNAJC12 is a chaperone upregulated in several cancer types." (PMID 26792175, 2016). "We also stained tumor sections for phosphorylated histone H3 and found that TCF7L1-Null tumors had significantly fewer dividing cells." (PMID 27333864, 2016). "Loss of TCF7L1 impaired growth and colony formation of HCT116 CRC cells and reduced tumor growth in a mouse xenograft model." (PMID 27333864, 2016). "TCF7L1 expression was upregulated in lines derived from metastatic tumours compared to primary tumours, while conversely both TCF7L2 and LEF1 were strongly downregulated in the metastatic lines." (PMID 27531891, 2016). "Principal component analysis revealed clear distinctions between both the HCT116 control vs. TCF7L1-Null cells, and the cultured cells vs. tumors, with strong similarity among replicates and more heterogeneity among tumor samples." (PMID 27333864, 2016). "Our results further indicate that molecules that are involved in Wnt signaling, including Tcf7L1, Frzb, and Wntless, were upregulated in DC-tumor fusions." (PMID 26605345, 2015). "TCF7L1, TEX13B, and DSCAML1 mutations, which were detected during exome sequencing, were not confirmed in subsequent Sanger sequencing of the primary tumor or any metastatic specimens." (PMID 24406431, 2014). "The change in Wnt effectors is likely an important driver of tumour-specific gene expression, as TCF/LEF binding motifs are enriched in tumour-specific active chromatin, and given that Lef1/Tcf7 are mostly transcriptional activators while Tcf7l1 is known to have mainly repressive functions." (PMID 37907668, 2023). "However, there was no published information as to the source of this aberrant expression of SDC2 and TCF7L1 in tumor biopsies from patients with MESO." (PMID 35127947, 2022). "The regulatory mechanism of TCF7L1 on tumor functional genes has been illuminated as well." (PMID 35127947, 2022). "Our meta-analysis of transcriptomics studies provides a clear picture of altered LEF/TCF gene expression, confirming TCF7L2 in normal and LEF1 expression in tumor tissue, but also higher than expected TCF7L1 in normal and relatively higher TCF7 expression in tumor tissue." (PMID 32403323, 2020). "In this study, the same tumor-promoting roles of TCF7L1 were observed in gastric cancer patients." (PMID 30811526, 2019). "A recent study provided evidence for a tumor-promoting role of TCF7L1 in skin." (PMID 31438551, 2019).